NEU3 (neuraminidase 3)
Diseases named in the same sentence as NEU3 in open-access papers (continued):
Sharing a sentence is not in itself a finding about the gene and the disease.
melanoma (5 papers, 2014 to 2021). A malignant, usually aggressive tumor composed of atypical, neoplastic melanocytes. "Overexpression of NEU3 is expected to cause hyposialylation, but gangliosides are overexpressed in different cancer types, such as breast and melanoma." (PMID 29912148, 2018). "NEU3 and GM1 and GM2 synthases, involved in ganglioside metabolism, were associated with melanoma cell proliferation and invasion." (PMID 34683168, 2021). "NEU3 has been shown to be overexpressed in a large number of cancer types including prostate cancer, melanoma, and ovarian cancer." (PMID 29912148, 2018). "We confirmed an overall higher expression of GD3 synthase (11.5-1.5-fold) and plasma membrane sialidase NEU3 (7–1.5-fold) in all melanoma cells than melanocytes." (PMID 25085576, 2014). "Similarly, the plasma membrane sialidase NEU3 has been shown to be highly expressed in human melanoma cell lines." (PMID 25085576, 2014). "Neu3 could be involved in melanoma malignancy by decreasing the levels of Neu5Ac-GM3." (PMID 27029067, 2016). "Therefore, we tried to assess if endogenous GM3 could be accessible to NEU3 activity in melanoma cells." (PMID 25085576, 2014). "Sialidase NEU3 could be involved in melanoma malignancy decreasing the levels of Neu5Ac-GM3." (PMID 25085576, 2014). "Therefore, the impact of NEU3 up-regulation in melanoma could be complex and should be further investigated in forthcoming works." (PMID 25085576, 2014). "As melanoma cells expressed high levels of GM3, the increase of NEU3 expression appeared a paradox." (PMID 25085576, 2014). "Moreover, other studies have reported a relationship between NEU3 and GD3 synthase genes that were significantly up-regulated in melanomas in comparison to melanocytes, possibly as a direct consequence of the increased expression of the transcriptional factor Sp1." (PMID 27029067, 2016).
prostate carcinoma (5 papers, 2013 to 2021). A carcinoma that arises from epithelial cells of the prostate gland. "It has been established that plasma membrane‐associated ganglioside sialidase (NEU3) is up-regulated in a variety of cancers, including colon and prostate cancers." (PMID 34234872, 2021). "Interestingly, while both bacterial neuraminidase and T. cruzi sialidase activate only MMP-2, the mammalian sialidase Neu-3, specific for SA α2,3 recognition observed in human prostate cancer models, is able to modulate both MMP-2 and MMP-9." (PMID 33891967, 2021). "More recently, these bacteria have been engineered to express numerous genes, including survivin, MDM2, Neu3 and STAT3 siRNA against prostate cancer in our laboratory." (PMID 23721095, 2013).
Tay-Sachs disease (5 papers, 2020 to 2025). GM2 gangliosidosis, variant B or Tay-Sachs disease is marked by accumulation of G2 gangliosides due to hexosaminidase A deficiency. "Bypassing the HexA/GM2AP-dependent degradation of GM2 to GM3 with Neu3 to yield GA2 facilitates the complete degradation of GA2 by HexB in the Tay-Sachs disease mouse model (Hexa-deficiency)." (PMID 37972730, 2023). "The mouse as a model organism only develops a Tay-Sachs disease phenotype when the sialidase enzyme neuraminidase 3 (encoded by Neu3), which is thought to facilitate GM2 degradation through this bypass pathway, is knocked out, in combination with the primary Hexa gene." (PMID 34757540, 2022). "GM2 accumulation triggers chronic neuroinflammation due to neurodegeneration-based astrogliosis and macrophage activity with the increased expression level of Ccl2 in the cortex of a recently generated Tay-Sachs disease mouse model Hexa-/-Neu3-/-." (PMID 40019557, 2025). "Early onset Tay-Sachs disease mouse model (Hexa−/− and Neu3−/−) mice was generated by crossing of Hexa−/− and Neu3−/− mice to investigate the role of NEU3 sialidase in GM2 ganglioside degradation." (PMID 32951593, 2020). "Therefore, we investigated distinct steps of autophagic flux using markers including LC3 and p62 in four different brain regions from the Hexa-/-Neu3-/- mice model of Tay-Sachs disease." (PMID 36928510, 2023). "And, as noted by Proia and colleagues might manipulation of NEU3 activity be a therapeutic strategy for GM1 gangliosidosis and Tay-Sachs disease?" (PMID 37972730, 2023).
cardiac hypertrophy (4 papers, 2020 to 2024). "Also the following tachycardia-specific miR-1183-regulated targets showed a cardiovascular association: the gene NEU3 with cardiac fibrosis and CHD, ZNRD1 with CHD, TRIM16 with cardiac hypertrophy, BIRC3 with ischemic preconditioning, ARRDC3 with cardiac hypertrophy, and MTAP with ischemic stroke." (PMID 35805966, 2022).
bladder cancer (3 papers, 2024 to 2025). "We also investigated the molecular mechanisms underlying the role of NEU3 in the invasive ability of bladder cancer cells." (PMID 38255300, 2024). "NEU3 is significantly upregulated in bladder cancer tissues compared to normal ones, and its overexpression has been shown to promote tumor cell invasion." (PMID 40252176, 2025). "Analysis of NEU3’s function using its siRNA-mediated knockdown revealed that NEU3 contributes to bladder cancer invasiveness." (PMID 38255300, 2024). "Here, using patient tissues and multiple bladder cancer cell lines, we show that the sialidase NEU3 is highly expressed in bladder cancer." (PMID 38255300, 2024). "In multiple invasive bladder cancer cells, we found that knockdown of NEU3 reduced the invasive ability." (PMID 38255300, 2024). "In this study, we focused on the invasiveness of bladder cancer and investigated the involvement of NEU3." (PMID 38255300, 2024). "NEU3 is highly expressed in bladder cancer tissues compared with normal tissues and promotes the invasive ability of invasive bladder cancers." (PMID 38255300, 2024). "Similarly, neuraminidase-inhibitors have shown therapeutic promise, as suppression of NEU3 has been found to inhibit the invasion of aggressive bladder cancer cells, positioning NEU3 as a potential target for treating refractory bladder cancer." (PMID 40252176, 2025). "Because NEU3 was found to be highly expressed in bladder cancer, we investigated whether it was involved in the invasive ability of bladder cancer." (PMID 38255300, 2024). "Knockdown of NEU3 reduced the invasive ability of bladder cancer cells." (PMID 38255300, 2024). "We found that NEU3 may be a target that controls the invasive ability of bladder cancer, but due to the limited number of patient samples, we were unable to directly prove this in cancer tissue." (PMID 38255300, 2024). "NEU3 may affect the invasiveness of bladder cancer cells; however, KK47, a superficial bladder cancer cell line, showed high expression and activity of NEU3." (PMID 38255300, 2024). "The results indicated that the expression of NEU3 is increased in bladder cancer tissues." (PMID 38255300, 2024). "In addition, experiments using several bladder cancer cells and normal mucosa-derived cells showed that NEU3 is highly expressed in cancer cells, and that knockdown of NEU3 inhibits the invasive ability of invasive bladder cancer cells." (PMID 38255300, 2024). "We demonstrate for the first time that NEU3 is highly expressed in bladder cancer." (PMID 38255300, 2024). "Our results show that NEU3 is involved in the malignancy of bladder cancer, and its suppression may lead to novel treatments for bladder cancer." (PMID 38255300, 2024). "The inhibition of NEU3 can suppress the invasion of invasive bladder cancer, and might be a novel therapeutic target for refractory bladder cancer." (PMID 38255300, 2024). "The finding that knock down of NEU3 results in decreased invasiveness, reduced phosphorylation of ERK and P13K and decreased expression of the androgen receptor provides insight into how elevated NEU3 activity may contribute to oncogenicity in the bladder cancer tissues studied." (PMID 40943651, 2025). "Thus, NEU3 is involved in the invasiveness of bladder cancer." (PMID 38255300, 2024). "Our results indicate that NEU3 positively functions in the malignancy of cancer, at least upstream of Ras/MAPK and PI3K/AKT, and we believe that it represents a new avenue for the treatment of bladder cancer." (PMID 38255300, 2024).
GM2 gangliosidosis (3 papers, 2023 to 2025). A group of recessively inherited diseases characterized by the intralysosomal accumulation of G(M2) GANGLIOSIDE in the neuronal cells. "We also created Neu3 KO alleles that combined with Hexa KO or KI alleles were expected to create acute and chronic models of GM2 gangliosidosis, respectively." (PMID 40916664, 2025). "We expected to create a severe phenotype similar to some of the available severe mouse models for GM2 gangliosidosis with HexA deficiency, i.e., SD (Hexb−/−) and double knockout TSD (Hexa−/-Neu3−/−) models." (PMID 38098938, 2023). "In mouse models of GM2 gangliosidosis, GM2 can also be catabolized by sialidases (Neu3) into GA2, which can then be broken down by β-HexA and β-HexB." (PMID 37834060, 2023). "Additionally, it is possible that in the absence of NEU3, both NEU4 and NEU1 may partially compensate for this sialidase loss, as all neuraminidase activity has been shown to be increased in mouse models of GM2 gangliosidosis." (PMID 38098938, 2023).
colorectal cancer (2 papers, 2017 to 2018). A primary or metastatic malignant neoplasm that affects the colon or rectum. "NEU3, a human plasma membrane-associated sialidase that specifically hydrolyzes sialic acids on gangliosides, is upregulated in colorectal cancer and plays an important role in malignancy." (PMID 29773994, 2018). "In HT-29 and HCT116 colorectal cancer cells, NEU3 silencing significantly reduced clonogenicity and downregulated stemness and Wnt-related genes, suggesting that Wnt signaling contributes to NEU3-induced tumorigenesis through maintenance of stem-like characteristics of these cells." (PMID 29773994, 2018). "Our recent finding that sialidase NEU3 actively promotes EGFR autophosphorylation and is responsible for the increased viability of colorectal cancer cells prompted us to investigate the effect of this sialidase overexpression in NSCLC." (PMID 29088281, 2017). "Following the initial finding that human sialidase NEU3 co-immunoprecipitates with EGFR in HeLa cells, it has been found that NEU3 is directly involved in EGFR desialylation in colorectal cancer, promoting receptor dimerization, and therefore EGFR activation." (PMID 29088281, 2017). "Our results are in contrast with those observed in colorectal cancer cells, where a significant increase in cell viability was observed in an EGFR-hyper-stimulated cell line upon NEU3 overexpression." (PMID 29088281, 2017).
fibrosis (2 papers, 2022 to 2025). the formation of excess fibrous connective tissue in an organ or tissue in a reparative or reactive process. "Conversely, aspirations of NEU3 (with levels corresponding to the level of NEU3 in a fibrotic mouse lung) induced fibrosis in male and female mice." (PMID 36613682, 2022). "Interestingly, the intestines of patients with inflammatory bowel disease, many of whom also develop fibrosis, were found to contain 8-fold more NEU3 than controls, while the concentration of GD1a, an NEU3 substrate, was 1/3." (PMID 40943651, 2025).
glioblastoma (2 papers, 2024). The most malignant astrocytic tumor (WHO grade IV). "NEU3 is downregulated in human glioblastoma cells, and siRNA-mediated NEU3 silencing in glioblastoma cells enhances their invasiveness compared to control cells." (PMID 38255300, 2024). "We observed that after CCl4 treatment, hepatocytes increased expression of both cytoplasmic and nuclear NEU3, as observed previously for epithelial cells, CHO cells, and glioblastoma cells." (PMID 39570922, 2024).
GM1 gangliosidosis (2 papers, 2018 to 2023). A rare lysosomal storage disorder characterized biochemically by deficient beta-galactosidase activity and clinically by a wide range of variable neurovisceral, ophthalmological and dysmorphic features. "By developing and characterizing a Neu3- and Glb1-double knockout mouse model to deplete Neu3, they found a drastically earlier onset of disease in mice, which now resembles more the infantile form of GM1 gangliosidosis in humans." (PMID 37972730, 2023). "However, the Neu4 and Neu3 KO mouse models do not develop massive lysosomal storage of any ganglioside or severe clinical phenotypes resembling those of the Glb1 KO mouse (model of GM1 gangliosidosis) or β-hexosaminidase deficient Hexb KO mouse (model of Sandhoff disease)." (PMID 30088207, 2018).
Hepatic steatosis (2 papers, 2019 to 2023). Steatosis is a term used to denote lipid accumulation within hepatocytes. "Meanwhile, intestine HIF2α could inhibit the expression of neuraminidase 3 (Neu3), thus substantially ameliorating hepatic steatosis, glucose intolerance and IR." (PMID 37303813, 2023). "Subsequent analysis suggested that hepatic steatosis developed as a result of decreased ceramide production in the intestine, a process involving a direct gene target of HIF-2, Neu3 (neuraminidase 3)." (PMID 30832409, 2019).
insulin-resistant diabetes mellitus (2 papers, 2018 to 2020). A type of diabetes mellitus related not to lack of insulin but rather to lack of response to insulin on the part of the target tissues of insulin such as muscle, fat, and liver cells. "Neu3 preferentially hydrolyses gangliosides and is involved in insulin signalling and insulin-resistant diabetes mellitus." (PMID 32251344, 2020).
lung carcinoma (2 papers, 2017 to 2023). "We analyzed NEU3 and EGFR mRNA levels using qPCR, by comparing mRNA levels in lung cancer cells with those observed in the healthy HSAEC1 lung cell line." (PMID 29088281, 2017). "Given the importance of EGFR activation in NSCLC pathogenesis, we investigated the effect of sialidase NEU3 overexpression on EGFR downstream pathway activation and TKI targeted therapies sensitivity in a series of lung cancer cell lines." (PMID 29088281, 2017). "In this work, we investigate the effect of sialidase NEU3 overexpression on EGFR pathways activation and EGFR targeted therapies sensitivity, in a series of lung cancer cell lines." (PMID 29088281, 2017). "Additionally, NEU3 is a promising biomarker for evaluating EGFR-targeted therapies in patients with NSCLC, and the expression level of GTs in lung cancer tumors may act as a biomarker for the diagnosis, prognosis, and treatment assessment." (PMID 37256139, 2023). "NEU3 and EGFR were not overexpressed in any of the analyzed lung cancer cell lines; NEU3 mRNA levels were never significantly higher than 1, while EGFR mRNA levels were found downregulated in all cases, with a highest value of 0.5." (PMID 29088281, 2017).
lupus (2 papers, 2016 to 2020). "Taken together, these findings suggest that the ST3Gal-1 and Neu3 enzymes in B cells are potential marers of lupus activity." (PMID 26981635, 2016). "Similarly, no study has been done to explore possible relationship between Neu1 and Neu3 on lupus blood cells and lupus disease activity." (PMID 26981635, 2016). "Fifth, high ST3Gal-1 and Neu3 levels of PMN cells and monocytes were possible indicators of the presence of lupus proteinuria and a high SLEDAI score." (PMID 26981635, 2016). "NEU1 and NEU3 protein expression within the kidney has not been analyzed in detail; however, we demonstrated NEU1 and NEU3 expression in the glomeruli of mouse renal sections appear to be higher in lupus mice with nephritis compared to lupus mice without nephritis." (PMID 32187230, 2020).
nonalcoholic steatohepatitis (2 papers, 2024 to 2025). "Moreover, a study using CCl4-induced liver damage showed that NEU3 inhibition reduced macrophage infiltration, pro-inflammatory cytokines and suppressed fibrosis markers, implicating it in the transition from steatosis to nonalcoholic steatohepatitis (NASH)." (PMID 41301440, 2025). "We find that sera from patients with nonalcoholic fatty liver disease (NAFLD) and nonalcoholic steatohepatitis (NASH) have elevated desialylation of a serum protein and patients with NAFLD have increased levels of NEU3." (PMID 39570922, 2024).
Obesity (2 papers, 2023 to 2025). Accumulation of substantial excess body fat. "NEU3 has been reviewed for its involvement in obesity and diabetes, though its impact on insulin sensitivity and metabolic regulation remains controversial and context-dependent." (PMID 41301440, 2025). "In obesity-induced intestinal hypoxia, HIF-2α increases the production of ceramide, to promote the expression of the key enzyme sialidase 3 encoding Neu3, which leads to the development of IR in obese mice induced by a high-fat diet." (PMID 37056675, 2023). "As such, targeting neuraminidases, particularly NEU1, NEU2, and NEU3, may offer novel therapeutic strategies for obesity, type 2 diabetes, and NAFLD." (PMID 41301440, 2025). "During obesity, HIF-2α activation in the intestine upregulates NEU3, enhancing ceramide levels through the salvage pathway and leading to hepatic lipid accumulation and liver inflammation." (PMID 41301440, 2025).
ovarian carcinoma (2 papers, 2012 to 2014). A malignant neoplasm originating from the surface ovarian epithelium. "The NEU3 gene expression is aberrantly elevated in several human cancers, including colon, renal, prostate, and ovarian cancers." (PMID 22815940, 2012).
renal carcinoma (2 papers, 2021 to 2022). A carcinoma arising from the epithelium of the renal parenchyma or the renal pelvis. "Similarly, NEU3 has been found to act as a positive regulator of β1-integrin-mediated cell migration in renal cancer cells." (PMID 35281276, 2022).
Sepsis (2 papers, 2022 to 2025). Sepsis is defined as life-threatening organ dysfunction caused by a dysregulated host response to infection. "Four subtypes of neutrophils were identified in the peripheral blood of sepsis, namely, the Neu1, Neu2, Neu3, and Neu4." (PMID 36304125, 2022).
Anxiety (1 paper, 2020). Intense feelings of nervousness, tension, or panic often arise in response to interpersonal stresses. "In addition, 4.5-month-old Hexa−/−Neu3−/− mice showed more anxiety-related behaviors compared with that in WT and single deficient Hexa−/− and Neu3−/− mice." (PMID 32951593, 2020).
Arthritis (1 paper, 2016). Inflammation of a joint. "Higher monocyte ST3Gal-1/Neu3 ratios were noted in the arthritis subgroup than those in the no-arthritis subgroup." (PMID 26981635, 2016).
Cognitive impairment (1 paper, 2023). Abnormal cognition is characterized by deficits in thinking, reasoning, or remembering. "Thus, Neu3 overexpression aggravated cognitive impairment in APP/PS1 mice, suggesting that increased GM1 levels accelerate the progression of AD." (PMID 37759382, 2023).
colorectal tumor (1 paper, 2025). "Notably, Neu2 and Neu3 represented the predominant neutrophil subtypes in colorectal tumor (CT) samples, with Neu2 exhibiting an N2‐like phenotype and Neu3 exhibiting an N1‐like phenotype." (PMID 40842663, 2025).
cutaneous melanoma (1 paper, 2021). A primary melanoma arising from atypical melanocytes in the skin. "The overexpression of NEU3 and GD3 synthase genes has been reported in cutaneous melanoma." (PMID 34683168, 2021).
head and neck squamous cell carcinoma (1 paper, 2022). A squamous cell carcinoma that arises from any of the following anatomic sites: lip and oral cavity, nasal cavity, paranasal sinuses, pharynx, larynx, and salivary glands. "In the case of Head and Neck Squamous Cell Carcinoma (HNSCC), elevated mRNA levels of NEU3 were found in tumor tissues in comparison to normal tissues." (PMID 36547200, 2022).